EGFR (epidermal growth factor receptor)
Diseases named in the same sentence as EGFR in open-access papers (continued):
Sharing a sentence is not in itself a finding about the gene and the disease.
tumor (continued). "Such a lymphocyte depleted microenvironment may explain the resistance of EGFR overexpressing cancers to tumour therapies, particularly to check-point inhibitor treatments." (PMID 35052732, 2021). "normal proteins overexpressed by tumor cells (e.g. EGFR, Muc-1, Her2/neu), iv)." (PMID 33722265, 2021). "Under hypoxic stress, epidermal growth factor receptor (EGFR) suppresses the maturation of tumor-suppressor-like miRNAs by phosphorylating protein argonaute-2 and subsequently reduces the binding of Dicer to protein argonaute-2, inhibiting miRNA processing from precursor miRNAs to mature miRNAs." (PMID 34884541, 2021). "Equivalent expression of total EGFR was observed in both tumor types." (PMID 33799686, 2021). "Multivariate Logistic analysis showed that male, thyroid transcription factor-1 (TTF-1) negative, smoking history and tumor cell proportion less than 30% were main factors that contributes to the low detection rate of EGFR gene mutation." (PMID 34034456, 2021). "Our data show overexpression of SGLT1 together with co-expression of EGFR in 77.5% of tumors, suggesting that EGFR kinase-independent function might contribute to tumor progression." (PMID 34445451, 2021). "In addition, EGFR plays a critical role in the progression of tumor malignancy, including survival and invasion, and thus facilitating tumor metastasis." (PMID 33440835, 2021). "Targets for tumor-specific targeting to several tumors are the epidermal growth factor receptor (EGFR), folic acid receptor, lectins, holo-transferrin, hyaluronic acid, cell type-specific peptides encoding the arginine, glycine, and aspartate (RGD) sequence, or antibodies against CD22 or CD30." (PMID 34439219, 2021). "This could explain why the existing data are ambiguous concerning whether tumor PD-L1 expression can predict the response to EGFR-TKI treatment." (PMID 33964931, 2021). "Furthermore, it is necessary to know the clinical characteristics of patients whose sputum contains a sufficient amount of tumor cells for the EGFR gene detection." (PMID 33757469, 2021). "In the first case, tumor cell proliferation continues to depend directly on EGFR signaling." (PMID 34634633, 2021). "Thus, spatial differences regarding EGFR activation and repercussions on tumor cell differentiation are governed at various levels including ligand resources and represent a determinant of EMT heterogeneity in HNSCC." (PMID 34771518, 2021). "Exosomal miR‐210 may play an important role in the development of resistance to osimertinib in the tumor microenvironment and serve as a therapeutic target to conquer this resistance in EGFR‐mutant NSCLC." (PMID 33939301, 2021). "At initial diagnosis of non-squamous NSCLC, EGFR mutation testing is recommended, using tumor tissue biopsies." (PMID 34638411, 2021). "Furthermore, ILT4 inhibition substantially potentiated the anti-tumor activity of PD-L1 inhibitor in the EGFR wild-type NSCLC subtype." (PMID 33537094, 2021). "In tumors, EGFR overexpression can trigger tumor invasion and metastasis." (PMID 33535618, 2021). "However, anti-tumor-specific EGFR and CD44 treatments will also activate immune cells for secondary killing in addition to direct inhibition of tumor aggregation or clustering." (PMID 33995681, 2021). "Moreover, in pancreatic cancer, myeloid cells induced PD-L1 expression on tumor cells by activating EGFR-MAPK pathway." (PMID 33413496, 2021). "Interestingly, most of these genes have been implicated in general mechanisms of tumor biology, such as SERPINF1, reported as an inhibitor of angiogenesis and tumor suppressor, ASAP2, an EGFR pathway activator, or ELN and KRT8 related to the process of EMT." (PMID 34758873, 2021). "For these 154 patients who had been detected the EGFR status, there were 3 patients with EGFR mutation-negative and 1 patient with positive mutation did not receive any anti-tumor drug." (PMID 33869057, 2021).
tumor (continued). "EGFR amplifications have been reported to indicate a much more aggressive tumor subpopulation." (PMID 34638714, 2021). "At the same time, gene expression profiles analysis in USP8 mutant and wild-type tumors revealed that counter regulatory mechanisms may fine-tune the EGFR-MAPK pathway in tumor corticotroph cells." (PMID 34439178, 2021). "To better understand the anti‐tumour mechanism of licochalcone A, we examined whether licochalcone A could affect EGFR signalling pathway." (PMID 33247550, 2021). "The goal of this study was to test the hypothesis that the use of 66Ga would permit specific imaging of EGFR-expressing xenografts 24 h after injection and enhance the tumor-to-blood ratio when compared with imaging using the short-lived 68Ga radioisotope." (PMID 33672373, 2021). "Cetuximab exhibits anti-tumor effects in human cancers via targeting EGFR." (PMID 33472170, 2021). "DCN suppresses tumor cell-mediated angiogenesis by inhibiting the endogenous production of vascular endothelial cell growth factor, similar to neutralizing antibodies directed toward the epidermal growth factor receptor (EGFR)." (PMID 33918979, 2021). "Furthermore, the EGFRvIII mutation is relatively frequent (in 20-40% of GBM tumours) but shows a tumour restricted expression pattern compared to wildtype EGFR." (PMID 34926242, 2021). "Such treatment strategies may overcome the CD8 T-cell exclusion phenotype and might be useful in cases where EGFR mutant tumours acquire resistance to inhibitors." (PMID 35052732, 2021). "Transcription factors like NOTCH1 (16%) and KMT2B (16%), UNC13C (14%), another tumor suppressor, ERCC2 (14%) involved in nucleotide excision repair pathway, were recurrently mutated, whereas genes like CDKN2A, MLH1, FGFR1, EGFR, etc. had a less than 10% mutation frequency." (PMID 34796107, 2021). "However, with the continuous emergence of drug resistance in EGFR inhibitors in clinic, design and synthesis of novel EGFR inhibitors have become an urgent work for anti-tumour drug discovery." (PMID 34074193, 2021). "Additionally, a substantially increased EGFR copy number in tumor tissue DNA compared to those in buccal DNA of OSCC patients was observed." (PMID 34298758, 2021). "Dsg2 is involved in tumor progression through the regulation of EGFR and Src kinase activity." (PMID 32989241, 2021). "In addition, the CAF-mediated EGFR signaling pathway plays promoting roles in tumor invasion and metastasis." (PMID 34108441, 2021). "EGFR is a tyrosine kinase receptor that is overexpressed in many tumor types, including GBC25–27." (PMID 33414368, 2021). "EGFR activation triggers the Ras-Raf-MEK-ERK cascade in tumor cells." (PMID 33805447, 2021). "Accordingly, it is possible that strategies to upregulate CDCA3 levels, particularly in CDCA3low tumours or upon the emergence of therapy resistance, might improve the response to EGFR TKIs and benefit patients." (PMID 34572879, 2021). "Moreover, combining EGFR inhibitor ES-072 with anti-CTLA4 immunotherapy results in an additive effect on both tumor growth and cytotoxic T cell activation." (PMID 33879767, 2021). "Consistent with the functions of YAP/TAZ in contributing to tumor resistance against EGFR-TKI therapies, these proteins are also required for the elastic modulus-dependent response to lapatinib, an FDA-approved human epidermal growth factor receptor 2 (HER2)-targeted kinase inhibitor." (PMID 33467099, 2021).
tumor (continued). "In these studies 3/6 and 2/9 EGFR-Ex20ins patients exhibited a tumor response." (PMID 34208111, 2021). "Interestingly, other comutant alterations included additional alterations in NRAS in 1 tumor, a rare A18T mutation (7.1%); PIK3CA in 2 tumors (16.7%); and EGFR in 1 tumor, also a rare D761N mutation (7.1%)." (PMID 34063999, 2021). "We hypothesize that this TKI-induced, tumor cell-autonomous reprogramming response may variably influence the participation of the immune microenvironment in the therapeutic responses to EGFR antagonists within individual HNSCC tumors." (PMID 33485341, 2021). "In view of the relatively rarity of EGFR-amplified gastro-oesophageal cancers, we suggest that international collaborative efforts may be required in order to facilitate prospective trials enriched for EGFR-amplified tumours based on liquid biopsy testing." (PMID 33199443, 2021). "This combination forced tumor cells into an EGFR-dependent state and blocked tumor recurrences." (PMID 33718169, 2021). "G1 can trigger GPER/EGFR signaling in malignant tumor cells." (PMID 33767999, 2021). "In accordance with the effect of D6 on tumor regression, D6 therapy suppressed the EGFR signaling activity: determined by immunoblotting analysis of isolated xenografts, D6 suppressed EGFR expression and relevant downstream effectors, e.g., (pS473)AKT and pERK1/2." (PMID 34903832, 2021). "It is self-explanatory that most patients, who were excluded from these pembrolizumab registration trials due to the results of EGFR test, carried exon 19 deletion or L858R substitution in the tumor tissue, while only a minority if any LC cases were represented by rare EGFR mutations." (PMID 33407806, 2021). "Nevertheless, because ctDNA testing has lower sensitivity than tumor genotyping, an EGFRm test using tumor tissue specimens should be conducted when an EGFR mutation is not detected in ctDNA." (PMID 33270375, 2021). "Our studies have raised the question of how EGFR status may be involved in tumor response to TLR8 agonists." (PMID 33452311, 2021). "A commonly reported reason for not performing an EGFR mutation analysis was the lack of sufficient suitable tissue or a low percentage of tumor cells." (PMID 34298851, 2021). "Deregulation of EGFR signaling has been reported in tumor progression in different cancers." (PMID 33827418, 2021). "Similarly, one additional investigation assessed EGFR status in 37 histologically diagnosed NSCLC patients with available tumor tissue, PF (supernatants and cell blocks), and serum." (PMID 34199799, 2021). "The much weaker kinase activity of EGFR vIII accounts for the increased level of tumor growth." (PMID 34582442, 2021). "At the tumor cell-intrinsic level, the EGFR mutant cell lines exhibited wide-ranging magnitude and kinetics of chemokine/cytokine induction upon treatment with osimertinib with some exhibiting marked and prolonged responses and other showing little or no induction of these factors." (PMID 34001994, 2021). "The changes observed in RTK protein levels in tumors of mice treated with cetuximab or with INC280 and trametinib were consistent with those observed for 89Zr-labeled antibody tumor uptake and collectively suggest a mechanism of resistance of this EGFR-expressing PDX to cetuximab." (PMID 32646879, 2021). "By TGZ’s direct targeting epidermal growth factor receptor (EGFR) to induce its internalization and degradation by the endo-lysosomal degradation machinery, growth arrest of tumor cells can be achieved by the subsequent inhibition of EGF-induced Akt phosphorylation." (PMID 34631571, 2021). "Another interpretation from our findings could be that patients with different EGFR statuses have distinct tumor biology." (PMID 33787673, 2021). "Treatment of cells showing high EGFR expression was chosen so that the 213Bi-anti-EGFR-MAb could bind to the surface of tumor cells, therefore taking advantage of the high linear energy transfer of the alpha emitter 213Bi13,14." (PMID 33737524, 2021).
tumor (continued). "Additionally, we found pathways related to tumor development or prognosis via MetaCore, which indicates that EGFR signaling plays a vital role in the recurrence of PRAD." (PMID 34064004, 2021). "Thus, it is possible that 14-3-3σ regulates the anoikis of tumor cells through the EGFR-dependent ERK signaling pathway." (PMID 33391517, 2021). "The PE020 sEVs were also isolated from a patient with an EGFR-mutant NSCLC tumor, yet the immuno-PCR method detected much less signal for its EGFR content than in sEVs from PE011, which was consistent with Western blot profiling data in which PE011 had a higher EGFR level in sEVs relative to PE020." (PMID 33671772, 2021). "We delineate that EGFR has important implications in cellular dedifferentiation rather than proliferation in both genetically linked tumor types." (PMID 34281526, 2021). "Additionally, activation of the HGF-MET pathway by overexpression and up regulation has been described as the escape resistance mechanism of tumor cells against inhibition of the EGFR, RAS-RAF-MEK, and Akt–mTOR (mammalian target of rapamycin) pathways." (PMID 33918490, 2021). "CTGF is a matricellular protein that binds to the EGFR and regulates tumour progression." (PMID 33407703, 2021). "Studies in BCs and CMTs have shown increased EGFR expression in mRNA and protein levels in in situ carcinomatous sites relative to invasive areas implying that EGFR plays a more important role in the primary stages of tumor development." (PMID 34679042, 2021). "Hence, according to molecular signaling, nobiletin inhibits tumor progression by inhibiting the EGFR/JAK2/STAT3 pathway and PD-L1 expression in NSCLC cells." (PMID 34576006, 2021). "Indeed, in a pre-clinical model using cell line in vivo assays, it was demonstrated that EGFR promotes the survival of PC-circulating tumor cells, while ERBB2 supports cancer cell growth in bones by promoting the RANK signaling pathway." (PMID 33918389, 2021). "In addition to acting on EGFR expressed on tumor cells, AREG has recently been shown to promote differentiation of T cells into TREGs within the tumor microenvironment." (PMID 34843542, 2021). "Western blotting analysis of tumor tissues afflicted with liver metastasis indicated that anlotinib could significantly inhibit EGFR and ABCB1 expression in vivo." (PMID 33754008, 2021). "Targeting epidermal growth factor receptor (EGFR), monoclonal antibodies cetuximab and panitumumab are effective therapeutics that shrink tumors for resectability or relieve symptoms from unresectable masses by repressing tumor growth." (PMID 33632198, 2021). "From a clinical point of view, tumor stage at diagnosis does not generally seem to correlate with the presence of EGFR mutations, but such mutations have been linked to the presence of multiple lung lesions and air bronchograms on imaging." (PMID 33435440, 2021). "To assess whether MSA could decrease the expression of EGFR in vivo, we investigated EGFR expression in tumor tissues by IHC staining." (PMID 34393797, 2021). "Thus, there is an urgent demand to develop novel anti‐tumour drugs or identify new therapeutic targets that can complement current EGFR‐targeted therapy." (PMID 33247550, 2021). "EGFR plays crucial roles in the proliferation, growth, repair and survival of tumor cells." (PMID 33658393, 2021). "The upregulation of EGFR T678 phosphorylation was also observed in the xenograft tumor tissue of parental H292 cells after 1 month of erlotinib treatment, in the xenograft tissues of H292/ER clones, and in human NSCLC tumors with acquired TKI resistance, compared with their parental counterparts." (PMID 34155348, 2021). "Additionally, the assay incorporates whole transcriptome sequencing of the tumor sample that allows for the detection of gene fusions and select special transcripts, including AR-V7, EGFR vIII, EGFRvIV, and MET exon 14 skipping events." (PMID 33889297, 2021).
tumor (continued). "The expression of several tumor-associated genes was reported to be triggered by the inhibition of PPAR-γ activity through EGFR-mediated PPAR-γ phosphorylation and degradation, which, in turn, promoted nuclear EGFR/NF-κB signaling activation." (PMID 34381712, 2021). "By utilizing two different Fab arms against EGFR and PD-L1, the trispecific molecule of this study might exhibit elevated tumor selectivity." (PMID 34040611, 2021). "Conceivably, inhibitors including the EGFR monoclonal antibody and tyrosine kinase inhibitors that block EGF-EGFR signaling and a cell cycle blocker could impede tumor growth." (PMID 34204797, 2021). "Despite the clinical activity of first–second–third generation of EGFR-TKIs, 5–25% of NSCLC patients with a tumor harboring EGFR-activating mutations do not respond to these targeted therapies." (PMID 34638411, 2021). "In order to increase the tumor specificity of the SNP complex toward lung cancer cells, the SNP complex was conjugated with an EGFR-targeted peptide GE11 and pH-sensitive fusogenic peptide GALA, in order to form a functional complex for genetic material delivery (GE11&GALA-DNA@SNPs)." (PMID 33805602, 2021). "The Brazilian series showed correlation of EGFR variations with increased tumor size." (PMID 35008677, 2021). "The 41BBζ transduced hCART (hCART41BBζ) armed with HER2 BiAb (HER2 hCART41BBζ) or armed with EGFR BiAb (EGFR hCART41BBζ) killed multiple tumor lines significantly better than control T cells and secreted Th1 cytokines/chemokines upon tumor engagement at effector to target ratio (E:T) of 2:1 or 1:1." (PMID 34290709, 2021). "The EGFR signaling pathway plays an important role in tumor growth and the progression of CRC." (PMID 34521767, 2021). "EGFR C797S, the most common EGFR mutation after second-line osimertinib treatment, was not identified in first-line treatment in the tumor study." (PMID 34638411, 2021). "Edema Tumor Volume ratio on the other hand, was significantly associated with survival duration in the EGFR and KRAS mutation-positive groups, but not in ALK mutation-positive group." (PMID 33747933, 2021). "EGFR wild type is associated with decreased expression of BMX/SOX9 and inadequate pericyte coverage in neovascularization, and such an incomplete vascular system exacerbates tumor tissue hypoxia and necrosis." (PMID 34566988, 2021). "Notably, both the 99mTc-2Rs15d and 99mTc-EGFR Nbs demonstrated high tumor uptake and rapid blood clearance but also a high renal uptake." (PMID 34575943, 2021). "In accordance, low decorin levels have been associated with large tumor size, poorer survival and greater risk of early recurrence (especially when combined with high EGFR expression) in lymph node-negative invasive breast carcinomas." (PMID 33924197, 2021). "Ab = 50% of tumors with a tumor score of 5, anti-EGFR Ab = 22.2% of tumors with tumor score of 5)." (PMID 34830971, 2021). "Moreover, some patients continued to benefit from EGFR‐TKIs after tumor progression than switching to chemotherapy." (PMID 33660941, 2021). "Systemic treatment with antibodies can trigger effects on tumor cells (over-) expressing designated surface antigens, like the epidermal growth factor receptor (EGFR), programmed cell death protein 1 (PD-1), its ligand (PD-L1), as well as the cytotoxic T lymphocyte-associated protein 4 (CTLA-4)." (PMID 34884998, 2021). "Additionally, silica coated cadmium selenide quantum dots (CdSe-Silica QDs) conjugated with McAb successfully achieve the specific recognition of EGFR-positive tumor cell lines." (PMID 34322025, 2021). "Similarly to the in vitro findings, our in vivo results indicated that the combination of SH003 and DTX suppressed tumor growth and decreased p-EGFR (Y1068) and p-STAT3 (Y705) expression compared with the control in the NSCLC xenograft model." (PMID 34445110, 2021).